UBN1 (ubinuclein 1)
Description:
Acts as a novel regulator of senescence. Involved in the formation of senescence-associated heterochromatin foci (SAHF), which represses expression of proliferation-promoting genes. Binds to proliferation-promoting genes. May be required for replication-independent chromatin assembly.
Synonyms: VT; VT4
Tractability: PROTAC: ubiquitination databases record sites on it; its protein half-life has been measured.
Gene: Protein-coding gene on chromosome 16 (4,846,665 to 4,882,401, forward strand). Ensembl gene ENSG00000118900.
Subcellular location: Nucleus, nucleoplasm; Nucleus, PML body; Cell junction, tight junction
Subcellular location (Human Protein Atlas): Nucleoplasm; Nuclear bodies
Pathways (Reactome):
Cellular responses to stimuli: Formation of Senescence-Associated Heterochromatin Foci (SAHF)
Gene Ontology:
Molecular function: protein binding
Biological process: DNA replication-dependent chromatin assembly; nucleosome assembly; regulation of chromatin organization
Cellular component: HIR complex; nuclear body; nucleoplasm; nucleus; bicellular tight junction; PML body
Genetic constraint (gnomAD): Loss-of-function variants: 13 observed, 107.14 expected, observed/expected ratio (o/e) 0.12, 90% interval 0.078 to 0.19. The synonymous counts are far from expectation, so gnomAD's model fits this gene poorly and the ratio says little. Missense variants: 1,579 observed, 1,449.3 expected, observed/expected ratio (o/e) 1.09, 90% interval 1.04 to 1.14. Synonymous variants: 719 observed, 586.53 expected, observed/expected ratio (o/e) 1.23, 90% interval 1.15 to 1.3.
Homologues: Orthologues: chimpanzee UBN1 (97% identical), macaque UBN1 (96% identical), guinea pig UBN1 (90% identical), dog UBN1 (89% identical), rat Ubn1 (87% identical), mouse Ubn1 (87% identical), pig UBN1 (87% identical), rabbit UBN1 (84% identical), tropical clawed frog ubn1 (43% identical), zebrafish ubn1 (13% identical). Paralogues in human: UBN2 (40% identical).
Diseases named in the same sentence as UBN1 in open-access papers:
UBN1 is named in the same sentence as 7 diseases in open-access papers, as found by Europe PMC text mining. Sharing a sentence is not in itself a finding about the gene and the disease. The quoted sentences say what the papers report.
heart failure (2 papers, 2011 to 2022). Inability of the heart to pump blood at an adequate rate to meet tissue metabolic requirements. "UBN1, NGF and FECH genes displayed similar statistically significant regulation (up or down regulated) in hearts samples from heart failure patients but expression of the three remaining genes (TMEM79, FBXW7 and SLC43A2) could not be quantified, probably because of their low expression in heart." (PMID 21731613, 2011). "Analysis of the leucocyte transcriptome in 294 patients without overt heart failure revealed that levels of FECH, TMEM79, FBXW7, NGFB, ALK, UBN1, and SLC43A2 in peripheral blood were able to predict ALVD with 87% accuracy and 100% precision." (PMID 35722087, 2022).
Alzheimer disease (1 paper, 2024). A progressive, neurodegenerative disease characterized by loss of function and death of nerve cells in several areas of the brain leading to loss of cognitive function such as memory and language. "Notably, reported delayed human diseases resulting from UBN1 overexpression encompass Alzheimer’s disease, Parkinson’s disease, and type 2 diabetes." (PMID 38726016, 2024).
herpesvirus infection (1 paper, 2019). "Recent studies have shown that the HIRA (histone cell cycle regulator) histone H3.3 chaperone complex, composed of HIRA, Ubinuclein 1 (UBN1), and Calcineurin-binding protein 1 (CABIN1), relocalizes to PML-NBs in response to replication-defective herpesvirus infection." (PMID 30901352, 2019).
tumor (2 papers, 2021 to 2023). "Exploring the function of H3.3 in PC (TCGA and the Human Protein Atlas), we found that expression of two HIRA complex components, proteins HIRA and UBN1, is increased in tumor compared to normal prostate tissue." (PMID 37638746, 2023). "The SENP1 expression level positively correlated with the expression levels of UBN1, SP3, SAP130, NUP98, NUP153 in 32 tumor types." (PMID 34276383, 2021).
UBN1 also shares sentences with these, for which no sentence is quoted: infection (2 papers); Parkinson disease (1); type 2 diabetes (1).